EZH2 (enhancer of zeste 2 polycomb repressive complex 2 subunit)
Diseases named in the same sentence as EZH2 in open-access papers (continued):
Sharing a sentence is not in itself a finding about the gene and the disease.
schizophrenia (6 papers, 2018 to 2025). A major psychotic disorder characterized by abnormalities in the perception or expression of reality. "We propose that EZH2 may contribute to schizophrenia risk at two distinct time points either through disruption in development leading to neurodevelopmental changes, or through anomalous reactivation of expression in the adult brain." (PMID 29501388, 2018). "A ceRNA network was built on highly intersected lncRNA-miRNA-mRNA which included one lncRNA, 2miRNAs (miR-26a-5p and miR-22-3p) and 2 mRNA (EZH2 and SIRT1) and concluded that network have the potential as diagnostic molecular signal in early schizophrenia." (PMID 39939309, 2025). "EZH2 plays a crucial role in the epigenetic silencing of cyclooxygenase‐2,38 an enzyme that is overexpressed in schizophrenia and BD as a result of immune response dysregulation." (PMID 39482996, 2024). "Future studies are necessary to find the interactions between HOXA-AS2, EZH2 and cyclooxygenase-2 in the context of schizophrenia." (PMID 31484957, 2019). "EZH2 has crucial roles in the epigenetic silencing of cyclooxygenase-235, an enzyme whose over-expression has been noted in schizophrenia as a result of immune response dysregulation." (PMID 31484957, 2019). "Bioinformatic analysis of existing datasets also demonstrated high activity of EZH2 during CNS development and perhaps more strikingly in the anterior cingulate cortex of individuals with schizophrenia when compared to controls." (PMID 29501388, 2018). "Moreover, analysis of RNA-seq data has shown a significant elevation in EZH2 levels in the anterior cingulate cortex of patients with schizophrenia compared to normal individuals." (PMID 31484957, 2019). "So, dysregulation of these lncRNAs might have synergic effects on the aberrant expression of EZH2 in patients with schizophrenia." (PMID 31484957, 2019). "We have not addressed directly the role of the CACNA1C schizophrenia risk SNP (rs1006737) to modulate the promoter nor its interaction with EZH2 in this communication." (PMID 29501388, 2018). "RNA-seq data obtained from PD_NGSAtlas, a reference database for epigenomic and transcriptomic data for psychiatric disorders, demonstrated a 3-fold increase in EZH2 expression in the anterior cingulate cortex of individuals with schizophrenia compared to controls." (PMID 29501388, 2018).
steatosis (6 papers, 2013 to 2026). Increased lipid within the cytoplasm of cells. "EZH2 overexpression in vivo rejuvenated livers in aged mice, reversing aging-associated gene expression profiles, decreasing steatosis and fibrosis, and improving glucose tolerance." (PMID 41512022, 2026). "The steatosis-related phenotypes are recapitulated when treated with 3-Deazaneplanocin A, an EZH2 inhibitor, suggesting a causal role of EZH2 in NAFLD development." (PMID 33193730, 2020). "Moreover, EZH2 overexpression in vivo rejuvenated livers in aged mice—reversing aging-associated global gene expression profiles, significantly reducing steatosis and fibrosis, and improving glucose tolerance." (PMID 41512022, 2026). "In the early in vivo work with EZH2 overexpression, just three weeks of overexpression led to approximately a 50% reversal in gene expression, steatosis, fibrosis, and impaired glucose tolerance, which had accumulated over an entire lifetime (~20 mo)." (PMID 41512022, 2026). "At the tissue level, we demonstrate that overexpression of EZH2 alone is sufficient to rejuvenate the liver in aged mice, significantly reducing fibrosis and steatosis, and improving glucose tolerance." (PMID 41512022, 2026). "In conclusion, the results of this study suggest that the defective activity of EZH2 can enhance the NAFLD development by favouring steatosis and the de-repression of the inflammatory genes and that of specific microRNAs." (PMID 24351808, 2013). "Importantly, EZH2 overexpression did reverse hallmarks of liver health back to a young mouse state, with both a decrease in steatosis and fibrosis to at least half the level of the old mouse livers." (PMID 41512022, 2026). "The steatosis in NASH mice was attenuated by treatment with UNC1999 and EPZ6438 as EZH2 inhibitors and obeticholic acid." (PMID 32370249, 2020).
type 1 diabetes (6 papers, 2021 to 2025). "By analyzing sequencing data of type 1 and type 2 diabetes patients from GEO Databases, EZH2 expression was found to be reduced in PBMC of both type 1 diabetes and type 2 diabetes patients." (PMID 38243324, 2024). "E3 Ub ligase FBW7 prevents type I diabetes in nonobese diabetic mice by mediating EZH2 ubiquitination." (PMID 37143582, 2023).
adrenocortical carcinoma (5 papers, 2019 to 2025). "EZH2 is overexpressed and associated with poor prognosis in adrenocortical carcinoma (ACC) and its inhibition reduces growth and aggressiveness of ACC cells in culture." (PMID 31363169, 2019). "In adrenocortical carcinoma, EZH2 is the most dramatically dysregulated histone modifier, and its overexpression is correlated to poor prognosis and tumor proliferation in patients." (PMID 38269250, 2023). "Additionally, EZH2 (Enhancer Of Zeste 2 Polycomb Repressive Complex 2 Subunit), a methyl transferase controlling the epigenetic silencing of specific genes and/or microRNAs by trimethylating Lys27 on histone H3, has been identified as the most deregulated histone modifier in adrenocortical cancer." (PMID 40229247, 2025). "The histone H3 methyl-transferase EZH2 gene is overexpressed in several cancer types, including adrenocortical carcinoma (ACC), a rare cancer still lacking a targeted therapy." (PMID 40229247, 2025).
astrocytoma (5 papers, 2012 to 2025). "In the paired analysis of astrocytoma, IDH-mutant, increased H3K27me3 and EZH2 expression was observed during progression, and these alternations could be associated with the malignant progression of astrocytoma, IDH-mutant." (PMID 39636550, 2025). "To elucidate the clinical value of the EZH2–H3K27me3 axis in astrocytoma, IDH-mutant, we analyzed the pathological and clinical characteristics of this entity." (PMID 39636550, 2025). "CBX6, CBX7 and EZH1 shared a similar pattern and correlated negatively with increasing astrocytoma grade, whereas the opposite occurred with EZH2 and PHF19." (PMID 24260522, 2013). "Further research based on the findings is necessary to validate the efficacy of H3K27me3/EZH2 for predicting the malignancy of astrocytoma, IDH-mutant and to explore the association of H3K27me3/EZH2 with the molecular features of CDKN2A/B HD or the radiological characteristics." (PMID 39636550, 2025). "Positivity for H3K27me3, especially double positivity for H3K27me3 and EZH2, could be a poor prognostic factor for astrocytoma, IDH-mutant." (PMID 39636550, 2025). "These oncogenic activities of EZH2 might be related to the malignancy in EZH2-positive astrocytoma." (PMID 39636550, 2025). "Among them, the expressions of EZH2 and PHF19 correlated positively with the astrocytoma grades, whereas the expressions of CBX7, CBX6 and EZH1 correlated negatively with astrocytoma grades." (PMID 24260522, 2013). "Furthermore, to reveal the mechanisms of H3K27me3 expression in astrocytoma, IDH-mutant, we also evaluated EZH2." (PMID 39636550, 2025). "Interestingly, changes in EZH2, PHF19, CBX7, CBX6 and EZH1 occurred progressively as astrocytoma grade increased." (PMID 24260522, 2013). "In line with previous results, we found strong EZH2 expression in GBMs whereas the expression was low in astrocytoma grade III and absent in astrocytoma grade II." (PMID 23077658, 2012). "Compared to EZH2, we found a stronger expression of AXL in astrocytoma grade II and III." (PMID 23077658, 2012).
brain cancer (5 papers, 2016 to 2022). A primary or metastatic malignant neoplasm affecting the brain. "3‐dezaneplanocin‐A (DZNep) is one of the EZH2 inhibitors and has significant antitumor activity in various cancer types, including breast, prostate, lung, liver, and brain cancer cells." (PMID 35253323, 2022). "EZH2 has been shown to play a role in GBM and MB, and EZH2 inhibitors have been evaluated in preclinical models of brain cancers." (PMID 34681949, 2021). "Therapeutic goals including cancer stem cells (CSC), phenotypic shifts, EZH2/AXL/TGF-β axis activation, miRNAs and exosomes are relevant to GBM metastasis to develop novel targeted therapeutics for GBM and other brain cancers." (PMID 29642503, 2018). "The authors also demonstrated the association of SSAT with maternal embryonic leucine zipper kinase (MELK) and the enhancer of zeste homolog 2 (EZH2), which are both necessary for stem cell maintenance, tumor growth, and resistance to ionizing radiation (IR) in brain cancer." (PMID 35682610, 2022).
coronary artery disease (5 papers, 2019 to 2023). "In endothelial cells there is reciprocity between MAPK7 signaling and EZH2 expression and disturbances in this reciprocal signaling associate with the induction of EndMT and severity of human coronary artery disease." (PMID 34493753, 2021). "Disturbance in the reciprocity between MAPK7 and EZH2 result in the induction of EndMT and associate to the degree of human coronary artery disease." (PMID 34493753, 2021). "Dysregulation in the reciprocity between MAPK7 activation and EZH2 expression is associated to the induction of EndMT and the severity of coronary artery disease." (PMID 34493753, 2021). "Moreover, the increase in DUSP-1 expression associates with increased EZH2 expression in coronary artery disease (r2 = 0.4541, p = 0.0030) and the increase in DUSP-1 expression tends to associate with decreased MAPK7 expression (r2 = 0.1686, p = 0.1016), although not significantly." (PMID 34493753, 2021). "In coronary artery disease, EZH2 expression levels are elevated and high EZH2 expression is associated with endothelial dysfunction." (PMID 34493753, 2021). "Here, we report that in the endothelium there is reciprocity between MAPK7 and EZH2 in the regulation of EndMT and in human coronary artery disease." (PMID 34493753, 2021). "Using this approach, we show that there is a disbalance in MAPK7 activity and EZH2 expression in coronary artery disease and that this disbalance is perturbed with increasing IMT." (PMID 34493753, 2021). "Both EZH2 and H3K27me3 were increased in heart tissue from patients with ischemic heart disease." (PMID 37504561, 2023). "In contrast, EZH2 expression is elevated in coronary artery disease and an increasing coronary artery intima-media thickness ratio associates with increased EZH2 expression (r2 = 0.4417, p = 0.004), suggesting reciprocity between MAPK7 and EZH2 in human coronary artery disease." (PMID 34493753, 2021). "Collectively, these data suggest that in coronary artery disease, the reciprocity between MAPK7 activity and EZH2 expression is regulated by miR-101." (PMID 34493753, 2021). "Moreover, the expression level of miR-101 associates with MAPK7 (r2 = 0.4262, p = 0.005) and tends to associate to EZH2 (r2 = 0.2304, p = 0.051) in coronary artery disease, where a negative association between MAPK7 and EZH2 expression (r2 = 0.2568, p = 0.038) is present." (PMID 34493753, 2021). "In human coronary artery disease, we assessed the expression levels of MAPK7 and EZH2 and found that with increasing intima/media thickness ratio, MAPK7 expression decreased, whereas EZH2 expression increased." (PMID 34493753, 2021). "Currently, it is elusive how the crosstalk between MAPK7 and EZH2 is regulated in the endothelium and whether the balance between MAPK7 and EZH2 is disturbed during intimal hyperplasia and coronary artery disease." (PMID 34493753, 2021). "Furthermore, we identify EZH2 as an epigenetic regulator of KLF15 along with DNA hypermethylation, and we propose a novel mechanism through which coronary heart disease reprograms the expression of both intermediate enzymes and upstream regulators of cardiac metabolism such as KLF15." (PMID 30089854, 2019).
craniosynostosis (5 papers, 2018 to 2023). Craniosynostosis is defined as the premature fusion of one or more cranial sutures leading to secondary distortion of skull shape resulting in skull deformities with a variable presentation. "EZH2 was significantly enriched for DEGs associated with lambdoid craniosynostosis in the primary model and male sex-stratified model." (PMID 36982425, 2023). "Of this pair, SUZ12 has not previously been associated with craniosynostosis, but there are several studies reporting associations between EZH2 and craniosynostosis." (PMID 36982425, 2023). "In our study, EZH2 was enriched as a regulator of DEGs associated with the lambdoid phenotype in our primary and male-stratified models, while this previous study found that EZH2 deletion caused coronal and metopic craniosynostosis." (PMID 36982425, 2023). "EZH2 deletion in mesoderm and neural crest tissue causes the mortality of embryos, while EZH2 deletion in mesenchyme causes several skeletal abnormalities such as craniosynostosis and bone volume repression." (PMID 33759287, 2021). "The conditional knockout of Ezh2 in mesenchymal precursors (using Prrx1-Cre) causes coronal craniosynostosis." (PMID 32916911, 2020). "EZH2 has also been implicated in premature suture closure in craniosynostosis cases that are accompanied by a mutation in TWIST1, where EZH2 deposits fewer H3K27me3 silencing marks on osteogenic genes when TWIST1 is deleted." (PMID 36982425, 2023). "Of relevance to craniosynostosis, studies of EZH2 have demonstrated that it plays an essential role in neural crest cells and craniofacial development." (PMID 32916911, 2020). "Conditional deletion of Ezh2 at E9.5 in posterior CM with Prx1Cre resulted predominantly in postnatal craniosynostosis." (PMID 29223978, 2018). "It should be noted that EZH2 mutations in humans cause Weaver syndrome, a phenotype that includes distinct facial dysmorphologies, but not craniosynostosis." (PMID 32916911, 2020). "TWIST-1 expression and function have been correlated with the epigenetic regulator Enhance of Zeste Homolog 2 (EZH2) in mediating SCS cranial bone cell growth and differentiation, where Ezh2 knockdown in the mesenchymal lineage leads to craniosynostosis and other skeletal deformities." (PMID 33298158, 2020). "Interestingly, the coronal craniosynostosis phenotype is not apparent in mice, in which Ezh2 is ablated in osteoblasts (using Sp7-Cre)), nor is it observed upon the loss of Ezh2 in cartilaginous tissues (using Col2-Cre)." (PMID 32916911, 2020).
embryonal rhabdomyosarcoma (5 papers, 2015 to 2022). A poorly circumscribed morphologic variant of rhabdomyosarcoma. "In embryonal Rhabdomyosarcoma and several other tumors, EZH2 is often deregulated and, in some cases, is associated with tumor malignancy." (PMID 34372908, 2021). "It was manifested that miR-101 tends to inhibit cell proliferation by downregulating the expression of the enhancers of zeste homolog 2 (EZH2) in lung cancer, bladder transitional cell carcinoma and embryonal rhabdomyosarcoma." (PMID 35741797, 2022). "EZH2 protein was found to have a sensitivity of 91.30% and specificity of 100% in distinguishing well-differentiated LMS from cellular leiomyoma, and a sensitivity of 92.86% and specificity of 100% in distinguishing well-differentiated embryonal rhabdomyosarcoma (ERMS) from fetal rhabdomyoma." (PMID 30120321, 2018).
HCMV infection (5 papers, 2023 to 2025). "Recent studies have linked high-risk HCMV infection to the upregulation of PGCCs, EZH2, and the induction of EMT plasticity in various cancers including ovarian cancer." (PMID 41463341, 2025). "Recent research has implicated high-risk HCMV infection in PGCC development, and EZH2 overexpression in 72% of OC cases, supporting HCMV’s role in OC tumour progression." (PMID 41463341, 2025). "Following HCMV infection of human mammary epithelial cells (HMECs), ovarian epithelial cells (OECs), and astrocytes, a subtle activation of Myc and EZH2 as well as polyploidy induction were observed." (PMID 38534385, 2024). "Several studies confirmed that HCMV infection has the potential to trigger Myc induction, foster stemness, and initiate pro-EZH2 pathways." (PMID 38534385, 2024). "EZH2 and Myc, pivotal regulators of cellular processes, gain significance in the context of oncoviruses and HCMV infections." (PMID 38534385, 2024). "Our findings highlight the presence of a potential link between HCMV infection, Myc/EZH2 upregulation and CEGBCs induction in vitro and in GBM biopsies." (PMID 37147437, 2023). "In this review, we highlighted the significance of EZH2 and Myc oncogenes in oncovirus and HCMV infections, and focused on indicating that HCMV might be classified as a potential oncovirus." (PMID 38534385, 2024). "Notably, recent studies suggest that the upregulation of EZH2 and myc may be induced by human cytomegalovirus (HCMV) infection." (PMID 38886655, 2024). "Collectively, our discoveries affirm the suggested tumorigenic properties of Enhancer of zeste homolog 2 (EZH2) and Myc upon HCMV infection." (PMID 38534385, 2024).
heart failure (5 papers, 2019 to 2024). Inability of the heart to pump blood at an adequate rate to meet tissue metabolic requirements. "Therefore, future mechanistic studies will explore the causative role of differential DNA methylation and EZH2 in heart failure pathogenesis and therapy." (PMID 30089854, 2019). "For instance, EZH2 is a target for many noncoding RNAs involved in the development of heart failure." (PMID 38584203, 2024). "The lncRNA NEAT1 recruits EZH2 to the Smad7 promoter, increases Smad7 methylation, and accelerates the development of heart failure and ventricular remodeling." (PMID 38584203, 2024). "In conclusion, our data suggest EZH2 as an attractive therapeutic target to reduce cardiac inflammation and limit heart failure development following MI." (PMID 37491334, 2023). "With regard to the underlying mechanism, our findings showed that Neat1 promoted the progression of cardiac fibrosis to heart failure by recruiting EZH2 to the promoter region of Smad7." (PMID 34980170, 2022). "Although mechanistic studies are required to determine the direct role of both DNA methylation and EZH2 in heart failure, defining the epigenetic and/or metabolic machinery contribute to precision-based interventions for ischemic cardiomyopathy." (PMID 30089854, 2019). "In heart failure, lncRNA NEAT1 was found to provide scaffolding between the enhancer of zeste homolog 2 (EZH2) and the Smad7 promotor region similar to lncRNA MALAT1, thereby decreasing the expression of Smad7 and leading to unbalanced TGFβ–driven fibrosis." (PMID 38485860, 2024).